CDK5RAP2 (CDK5 regulatory subunit associated protein 2)
Diseases named in the same sentence as CDK5RAP2 in open-access papers (continued):
Sharing a sentence is not in itself a finding about the gene and the disease.
Primary microcephaly (19 papers, 2012 to 2025). Head circumference below 2 standard deviations below the mean for age and gender at birth. "Biallelic variants in the CDK5RAP2 gene, an ultra-rare cause of autosomal recessive primary microcephaly, lead to Primary Autosomal Recessive Microcephaly 3 (MCPH3)." (PMID 41153337, 2025). "Patient-derived Hi-Q brain organoids recapitulate distinct forms of developmental defects: primary microcephaly due to a mutation in CDK5RAP2 and progeria-associated defects of Cockayne syndrome." (PMID 39702477, 2024). "A substantial number of 12 of these genes were deregulated, most significantly ASPM, a well-characterized MCPH gene, and CDK5RAP2, mutations in which have been reported in patients with primary microcephaly and/or Seckel syndrome." (PMID 35099000, 2022). "Mutations in CDK5RAP2 have been shown to reduce the number of NPCs and have been linked to primary microcephaly." (PMID 35371036, 2022). "During interphase, Astrin interacts with centrosomal protein (CEP) 72 and primary microcephaly (MCPH) associated protein CDK5RAP2 (CDK5 regulatory subunit associated protein 2)." (PMID 32984344, 2020). "Mutations in the CDK5RAP2 gene can cause primary microcephaly due to abnormalities in cell division during neurogenesis." (PMID 27158822, 2016). "Together, these findings indicate that the loss of the C-terminal SMC and p35- and pericentrin-binding motifs are sufficient to cause CDK5RAP2-associated primary microcephaly." (PMID 26550838, 2015). "So far, no families have been described in which patients with the same CDK5RAP2 mutation had either primary microcephaly or Seckel syndrome." (PMID 26436113, 2015). "Primary microcephaly (MCPH) associated proteins CDK5RAP2, CEP152, WDR62 and CEP63 colocalize at the centrosome." (PMID 26297806, 2015). "In the present study, we have identified the novel nonsense mutation c.4441C > T (R1481*) in the CDK5RAP2 gene in a homozygous constellation in two boys of Italian descent with primary microcephaly." (PMID 23587236, 2013). "Plays a critical role in cell cycle; loss of CDK5RAP2 function associated with reduced numbers of neural progenitor cells (NPCs); mutations in CDK5RAP2 are linked to primary microcephaly; mutations in CDK5RAP2 were identified in case of vertically transmitted ZIKV infection with congenital syndrome." (PMID 35371036, 2022). "Mutations of CDK5RAP2 are the cause of both primary microcephaly and Seckel syndrome." (PMID 28004182, 2017). "Therefore, our report of a Somali child with primary microcephaly and a novel E234X mutation confirms CDK5RAP2 as a disease gene with clinical relevance outside the Pakistani population." (PMID 22887808, 2012). "Rs13301996 is intronic to CDK5RAP2, which encodes a regulator of CDK5 activity, interacts with CDK5R1 and pericentrin (PCNT), plays a role in centriole engagement and microtubule nucleation and has been linked to primary microcephaly and Alzheimer’s disease." (PMID 34165540, 2021). "Knowledge of this expression of different forms of CDK5RAP2 in human, rat and mouse is essential in selecting the appropriate model for studies of CDK5RAP2 and primary microcephaly but our findings further indicate the evolutionary divergence of mouse from the human and rat species." (PMID 26550838, 2015). "Likewise, CDK5RAP2 mutations that disrupt its centrosomal localisation domain are also associated with primary microcephaly, with or without dwarfism." (PMID 41373726, 2025).
autosomal recessive primary microcephaly (10 papers, 2013 to 2025). "Homozygous or compound heterozygous variants in the CDK5RAP2 gene cause Primary Autosomal Recessive Microcephaly 3 (MCPH3) (MIM # 604804)." (PMID 41153337, 2025). "Loss-of-function variants of Cdk5rap2 are associated with primary autosomal-recessive microcephaly (MCPH)." (PMID 39137170, 2024). "CDK5RAP2 is also known as a causative gene for autosomal recessive primary microcephaly." (PMID 36164503, 2022). "CDK5RAP2 (CEP215) encodes a centrosomal protein which is known to be essential for centrosomal cohesion and proper spindle formation and has been shown to be causally involved in autosomal recessive primary microcephaly." (PMID 26436113, 2015). "So far, five genes associated with autosomal recessive primary microcephaly (MCPH) have been identified in patients: MCPH1, CDK5RAP2, ASPM, CENPJ, and STIL/SIL." (PMID 28933765, 2017). "Autosomal Recessive Primary Microcephaly (MCPH) is one of those, for which seven loci (MCPH1-MCPH7) with the corresponding genes (MCPH1, WDR62, CDK5RAP2, CEP152, ASPM, CENPJ, and STIL) have been reported so far." (PMID 24148351, 2013).
Seckel syndrome (7 papers, 2015 to 2024). A rare autosomal recessive inherited syndrome caused by mutations in the ATR gene, RBBP8 gene, CENPJ gene, CEP152 gene, CEP63 gene, NIN gene, DNA2 gene, or TRAIP gene. "The analysis of brain organoids from a patient with Seckel syndrome and homozygous CDK5RAP2 mutation determined defects in neurogenesis caused by an altered balance of symmetric and asymmetric cell division of neuronal precursor cells." (PMID 35099000, 2022). "In this study, we present genetic and functional evidence that biallelic mutations in CDK5RAP2 cause Seckel syndrome." (PMID 26436113, 2015). "Furthermore, mouse models mimicking Cdk5rap2 mutations found in Seckel syndrome are also characterized by low centrosomal Pcnt levels and premature disengagement." (PMID 30035751, 2018). "In summary, we describe CDK5RAP2 mutations in patients with Seckel syndrome, provide evidence that CDK5RAP2 function is necessary for centrosomal integrity and proper cell division, and propose the possibility of a digenic inheritance in centrosomal disorders such as Seckel syndrome." (PMID 26436113, 2015). "We continued our molecular analysis of CDK5RAP2 in 10 additional patients with the clinical diagnosis of Seckel syndrome." (PMID 26436113, 2015). "Ten genes have been reported for Seckel syndrome so far, and four of them (CENPJ, CEP152, CDK5RAP2 and CEP63) are also involved in MCPH." (PMID 34068194, 2021).
anemia (4 papers, 2013 to 2024). A reduction in the number of red blood cells, the amount of hemoglobin, and/or the volume of packed red blood cells. "Using an ex vivo differentiation system, we found that CDK5RAP2‐deficient erythroblasts are impaired in enucleation: they have fewer but larger enucleating erythroblasts, which recapitulates the observed macrocytic anemia in adult mice lacking CDK5RAP2." (PMID 35678476, 2022). "Mice lacking the conserved centrosome component, CDK5RAP2, are likely to have defective erythroid differentiation because they develop macrocytic anemia." (PMID 35678476, 2022).
Zika Virus Infection (4 papers, 2017 to 2022). "In a vertically transmitted ZIKV infection case with microcephaly and other congenital abnormalities, a mutation in cyclin-dependent kinase 5 regulatory subunit-associated protein 2 (CDK5RAP2) was detected." (PMID 35371036, 2022). "We used molecular and microbiological assessments to report the initial case of vertically transmitted ZIKV infection with congenital syndrome associated with a neurological syndrome, where a mutation in the CDK5RAP2 gene was also identified." (PMID 33815457, 2021). "For that reason, we hypothesized that CDK5RAP2 variants might interact as a second hit effect in the existence of congenital ZIKV infection as in the present case their father is a carrier of p.Thr274LysfsTer27 and p.Glu275ArgfsTer16 without any specific phenotype." (PMID 33815457, 2021).
Alzheimer disease (3 papers, 2021 to 2023). A progressive, neurodegenerative disease characterized by loss of function and death of nerve cells in several areas of the brain leading to loss of cognitive function such as memory and language. "Notably, ptn and cdk5rap2, which were demonstrated to be associated with Alzheimer’s disease, were upregulated in the IR+ differentiation group." (PMID 36551187, 2022).
breast carcinoma (3 papers, 2016 to 2024). "Furthermore, comparative studies to human breast cancer would be highly prioritised since further studies are required to understand the potential involvement of CDK5RAP2 and MEGF9 in breast cancer." (PMID 27158822, 2016). "Two human breast cancer genes, BRCA1 and BRCA2, and the CDK5RAP2 gene involved in the cell cycle regulation, have been linked with increased odds of mammary tumours in the English Springer Spaniel, a breed at high risk of mammary tumours which is closely related to the ECS." (PMID 38233914, 2024). "The CDK5RAP2, MEGF9, snoRNA and tumour antigen pathways identified in this study could thus potentially also play roles in human breast cancer." (PMID 27158822, 2016).
mammary tumours (3 papers, 2016 to 2024). "The CDK5RAP2 could therefore have a key role in the development of mammary tumours and we suggest that further studies should be performed in both dogs and women to investigate CDK5RAP2 and its possible effect on disease and treatment response." (PMID 27158822, 2016).
colon cancer (2 papers, 2024 to 2025). "In colorectal cancer, MORC2 binds to RBM39 to promote alternative splicing of pre-CDK5RAP2, converting CDK5RAP2 L into a variant CDK5RAP2 S. CDK5RAP2 S promotes invasion and metastasis of colon cancer cells in vitro and in vivo." (PMID 39048555, 2024). "CDK5RAP2 has been found to be aberrantly expressed in oral squamous cell carcinoma and colon cancer, and promotes the EMT and metastasis of cancer cells." (PMID 40835789, 2025). "Taken together, these findings demonstrate that CDK5RAP2 S promotes metastasis of colon cancer cells in vivo." (PMID 39048555, 2024). "Taken together, MORC2 and RBM39 promote EMT, migration and invasion of colon cancer cells via CDK5RAP2 S." (PMID 39048555, 2024). "Next, we investigated the molecular function of the two CDK5RAP2 isoforms in colon cancer cells." (PMID 39048555, 2024). "In this study, our data demonstrate the functional links between MORC2, RBM39 and the downstream CDK5RAP2 whose alternative splicing they regulate in EMT and metastasis of colon cancer cells." (PMID 39048555, 2024). "To investigate the mechanism by which CDK5RAP2 S and PHF8 promote EMT in colon cancer, we performed RT-qPCR experiments." (PMID 39048555, 2024). "Here, we identified a novel target gene CDK5RAP2, whose alternative splicing was regulated by RBM39 and MORC2, contributing to a better understanding of the mechanisms of RBM39 and MORC2 in colon cancer." (PMID 39048555, 2024). "Collectively, these data indicate that CDK5RAP2 S specifically interacts with PHF8, and that PHF8 may promote EMT in colon cancer cells." (PMID 39048555, 2024). "Whereas overexpression of CDK5RAP2 S down-regulated E-cadherin and up-regulated N-cadherin, Vimentin, Zeb1, Slug and Twist1 expression, indicating that CDK5RAP2 L and CDK5RAP2 S might have different roles in EMT of colon cancer cells." (PMID 39048555, 2024). "By overexpression of CDK5RAP2 L or CDK5RAP2 S after CDK5RAP2 knockdown via lentiviral infection in SW480-luc cells, we found that CDK5RAP2 S, but not CDK5RAP2 L promoted the migration and invasion of colon cancer cells." (PMID 39048555, 2024).
Intellectual disability (2 papers, 2015 to 2025). "Homozygous mutations in the CDK5RAP2 gene cause autosomal recessive primary microcephaly type 3 (MCPH3), a rare developmental disorder of the brain characterized by a pronounced reduction of brain volume, particularly of the neocortex, as well as intellectual disability." (PMID 26322982, 2015).
neuroblastoma (2 papers, 2006 to 2016). Neuroblastoma (NB) is the most common solid, extracranial childhood tumor. "Interestingly, when compared with neuroblasts, the neuroblastomas have more genes in common with the self-renewing neural stem cells (535 versus 145), among others the neurogenesis genes ASCL1, GSS, STAT3, UTP11L, ENAH, APBB2, CDK5RAP2, and LARGE." (PMID 16989664, 2006).
oral squamous cell carcinoma (2 papers, 2023 to 2025). "In oral squamous cell carcinoma (OSCC), a highly aggressive and frequently lethal malignancy, the role and action mechanism of the microtubule regulatory protein CDK5RAP2 have not been fully understood." (PMID 36774351, 2023).
Azoospermia (1 paper, 2025). Absence of any measurable level of sperm,whereby spermatozoa cannot be observed even after centrifugation of the semen pellet. "In humans, a homozygous missense variant in CDK5RAP2 was associated with non-obstructive azoospermia, supporting its role in testicular function." (PMID 41373726, 2025).
cataract (1 paper, 2021). Partial or complete opacity of the crystalline lens of one or both eyes that decreases visual acuity and eventually results in blindness. "We also observed a previously undefined defect in retinal development causing microphtalmia in Cdk5rap2-deficient embryos, in agreement with cataracts and ocular abnormalities observed in MCPH3 patients." (PMID 34237032, 2021).
chronic eosinophilic leukemia (1 paper, 2017). "Thus, we have identified the 17-bp component of the linker for the CDK5RAP2-PDGFRα fusion gene in a chronic eosinophilic leukemia patient as a homologous sequence in Marinobacter sp. Hb8, R. fascians D188, Rhodococcus sp." (PMID 28593047, 2017).
Cockayne syndrome (1 paper, 2024). A multisystem condition characterized by short stature, a characteristic facial appearance, premature aging, photosensitivity, progressive neurological dysfunction, and intellectual deficit. "Although we used the same number of hiPSC (Healthy control, CDK5RAP2-mutated, and Cockayne syndrome) to generate Hi-Q brain organoids, age-matched (30-day old organoids) CDK5RAP2 patient-derived organoids (Hereafter CDK5RAP2 organoids) were smaller in size." (PMID 39702477, 2024).
colorectal cancer (1 paper, 2024). A primary or metastatic malignant neoplasm that affects the colon or rectum. "Our findings not only provide a novel mechanism but also suggest a treatment strategy of targeting the MORC2/RBM39/CDK5RAP2 axis for colorectal cancer therapy." (PMID 39048555, 2024). "We also found decreased expression of CDK5RAP2 L and increased expression of CDK5RAP2 S in colorectal cancer tissues." (PMID 39048555, 2024). "In summary, our results reveal a novel mechanism by which MORC2 promotes colorectal cancer development by promoting the isoform switch of CDK5RAP2 L to CDK5RAP2 S through interacting with RBM39." (PMID 39048555, 2024). "However, the role and mechanism of CDK5RAP2 S in colorectal cancer remain elusive." (PMID 39048555, 2024). "Here, our results indicate that CDK5RAP2 S regulated by MORC2 and RBM39 promotes colorectal cancer progression." (PMID 39048555, 2024). "However, the role and mechanism of CDK5RAP2 S in colorectal cancer progression remain unclear." (PMID 39048555, 2024). "Taken together, our findings uncover a novel mechanism by which MORC2 promotes colorectal cancer metastasis, through RBM39-mediated pre-CDK5RAP2 alternative splicing and highlight the MORC2/RBM39/CDK5RAP2 axis as a potential therapeutic target for colorectal cancer." (PMID 39048555, 2024).
congenital cataracts (1 paper, 2023). "Therefore, variants of CDK5RAP2 may also cause multi-organ phenotypes, as suggested by the reports of patients with CDK5RAP2 variants manifesting CM along with sparse eyebrows, congenital cataracts, and pigmentary abnormalities." (PMID 36831309, 2023).
epilepsy (1 paper, 2023). A brain disorder characterized by episodes of abnormally increased neuronal discharge resulting in transient episodes of sensory or motor neurological dysfunction, or psychic dysfunction. "SVA-lncRNA AK057321 upregulates a wide variety of neurodevelopmental and neurological disease genes containing intronic SVAs beyond CDK5RAP2 including SCN8A, an epilepsy and intellectual disability sodium channel gene with a human-specific intronic SVA_D." (PMID 36997626, 2023).
glioblastoma (1 paper, 2018). The most malignant astrocytic tumor (WHO grade IV). "Three of these Fyn-induced PKA interactors, AKAP9, PDE4DIP, and CDK5RAP2, were validated biochemically and were shown to exist in complex with Fyn and PKA in a glioblastoma cell line." (PMID 30274258, 2018).
lymph node metastasis (1 paper, 2023). "Our analysis revealed that CDK5RAP2 expression was significantly increased in patients with higher clinical stages and higher number of lymph node metastasis." (PMID 36774351, 2023).
macrocytic anemia (1 paper, 2022). Anemia that is characterized by increased red blood cell volume. "Here, we show that fetal liver‐derived, CDK5RAP2‐deficient erythroid progenitors generate fewer and larger reticulocytes, hence recapitulating features of macrocytic anemia." (PMID 35678476, 2022). "While centrosomal CDK5RAP2 is not essential for gamma‐tubulin recruitment during the mammalian cell cycle, its absence causes erythroid enucleation defects leading to macrocytic anemia." (PMID 35678476, 2022). "Together, our findings elucidate the underlying cellular mechanism for the macrocytic anemia observed in mice in the absence of CDK5RAP2." (PMID 35678476, 2022). "In summary, mice lacking CDK5RAP2 show a mild macrocytic anemia and this phenotype can be recapitulated using an ex vivo erythroid differentiation system." (PMID 35678476, 2022).
Mondini dysplasia (1 paper, 2023). "This cochlear simplification, called Mondini dysplasia, is one of the hallmarks of CDK5RAP2-PM and suggests that CDK5RAP2 is crucial for ear development, as shown by its expression in the fetal cochlea." (PMID 37443841, 2023).
preeclampsia (1 paper, 2022). Preeclampsia is a hypertensive disorder of pregnancy that is characterized by new-onset hypertension with proteinuria presenting after 20 weeks of gestation, and depending on mild or severe forms may initially present with severe headache, visual disturbances, and hyperreflexia. "The highest observed to expected ratio value was seen for CDK5RAP2, a regulator of CDK5 (cyclin-dependent kinase 5) activity, which is implicated in preeclampsia via the regulation of Nestin, a cytoskeleton protein expressed in podocytes that serve as barriers to protein leakage." (PMID 35860693, 2022).
cancer (7 papers, 2016 to 2025). A tumor composed of atypical neoplastic, often pleomorphic cells that invade other tissues. "Depletion of CDK5RAP2 in OSCC cells inhibits tumorigenesis and migration, and reduces the expression of markers associated with cancer stem cells." (PMID 36774351, 2023). "Additionally, the expression of CDK5RAP2 is regulated by a signalling cascade called the canonical Wnt pathway, which is known to be involved in cancer development and metastasis." (PMID 36774351, 2023). "This region spans the CDK5RAP2 (CDK5 Regulatory Subunit Associated Protein 2) and parts of the MEGF9 (Multiple Epidermal Growth Factor-Like Domains Protein 9) gene, both with previous connections to cancer." (PMID 27158822, 2016). "To further investigate the correlation between CDK5RAP2 expression and OSCC clinical characteristics, we analyzed the data based on cancer stages and lymph node metastasis status." (PMID 36774351, 2023). "Initially, qRT-PCR analysis confirmed the RNA interference by siRNA targeting CDK5RAP2, MAD1L1, and RGCC (p< 0.05) in the COAD-derived cancer cell lines of HCT116 and SW480." (PMID 38143740, 2023). "Overall, these findings suggest that CDK5RAP2 is not only a potential biomarker for progression in OSCC, but also a potential target for developing new therapies for this type of cancer." (PMID 36774351, 2023). "Depletion of CDK5RAP2 inhibits the tumorigenesis and migration of OSCC cells and alters the OSCC cancer stem (-like) cell (CSC) signature." (PMID 36774351, 2023).